IL6 (interleukin 6)
Diseases named in the same sentence as IL6 in open-access papers (continued):
Sharing a sentence is not in itself a finding about the gene and the disease.
cancer (continued). "Sustained activation of IL-6/JAK/STAT3 signaling is an important factor in the development of cancer induced by inflammation." (PMID 36995541, 2023). "CAFs were the major regulators of IL-6 in TME and secreted much higher levels of IL-6 than cancer cells, TAMs, or normal fibroblasts." (PMID 36764954, 2023). "We observed that IL-6 promoted cancer stemness, as evidenced by the dramatic increase in NANOG expression." (PMID 37987305, 2023). "Cancer cells are able to produce cytokines such as granulocyte colony-stimulating factor (G-CSF) and IL-6, thus promoting neutrophils proliferation." (PMID 36661728, 2023). "Here, we demonstrate that docetaxel injures stromal cells, which release protumor cytokines, IL-6 and granulocyte colony stimulating factor (G-CSF), that in turn invoke dormant cancer outgrowth both in vitro and in vivo." (PMID 37699010, 2023). "In cancer, the expression of inflammatory signals, such as TNFα, IL-1β, and IL-6, are crucial indicators of sensitivity to chemotherapy and patient survival." (PMID 36672449, 2023). "IL-6 acts directly on cancer cells to induce the expression of STAT3 target genes, including Cyclin D1, BCL2-like protein 1 (BCL-xL), VEGF, MMPs, IL-10, and TGF-β, thereby contributing to the maintenance of CSC properties." (PMID 37853413, 2023). "NK-LAAO treatment activates the Panx1/iCa2+ signaling pathway to potentiate cancer cells to induce IL-6 expression, leading to cytotoxic tolerance and acquisition of the metastatic phenotype." (PMID 37385076, 2023). "Moreover, IL-6 may increase the risk of cancer in people with excessive body weight." (PMID 36835557, 2023). "Many immune and nonimmune cells, such as T cells, monocytes, macrophages, dendritic cells, and some cancer cells -such as CC cells- produce IL-6." (PMID 38064478, 2023). "There have been several reports on the prognostic significance of plasma IL-6 in ICI-treated patients with various cancers, including NSCLC; however, the clinical significance of its receptors, sIL-6R or sgp130, in the plasma has not been clarified." (PMID 38469154, 2023). "Increased values of IL-6 in the serum of cancer patients have also been identified in other studies." (PMID 37373987, 2023). "The other pathways of upregulation in multiple cancer types are allograft rejection (n = 28), IL‐6/JAK/STAT3 signalling (n = 24), inflammatory response (n = 23), ROS pathway (n = 22) and TNF‐α signalling through NF‐kB (n = 14)." (PMID 37097039, 2023). "Taken together, the Western blot analysis results suggested that 11c treatment inhibits the constitutive and IL-6-induced STAT3 phosphorylation in cancer cells." (PMID 37103357, 2023). "Given the extensive clinical experience with IL-6 inhibitors, and the pressing need to improve upon existing immunotherapies, combination of ICIs with approved anti-IL-6/IL6R agents warrants investigation in cancer patients." (PMID 36599350, 2023). "Altogether, the data support the fact that the progranulin–IL-6–sortilin axis was collectively upregulated in cancer cells exposed to human-based growth conditions using the PDS model." (PMID 38136303, 2023). "NET accumulation leads to an upregulation of proinflammatory adhesion molecules (ICAM-1, VCAM-1, and E-selectin) as well as proinflammatory cytokines (IL-1β and IL-6) in ECs, which can trigger organ failure due to hypo-perfusion of organs in cancer patients." (PMID 37222464, 2023). "This study identified IL-6 as a crucial cytokine in RBMS1 overexpression, demonstrating its involvement in promoting migration and invasion of cancer cells through IL-6 transactivation and JAK2/STAT3 downstream signaling pathway activation." (PMID 37755304, 2023). "Together with chronic inflammation, there is an augmentation in the secretion of tumor necrosis factor (TNF) and the cytokine interleukin 6 (IL-6), which contributed to cancer development, progression and metastasis." (PMID 37374075, 2023).
cancer (continued). "CAFs from tumors co-cultured with cancer cell lines increase cancer cells’ secretion of IL-6 and IL-8, the invasive capacities of MDA-MB-231 cells, and the angiogenic capacities of HUVEC cells." (PMID 37046676, 2023). "In cancer, IL-6 stimulates proliferation, survival, angiogenesis, TME immunosuppression, radioresistance, invasiveness and metastasis." (PMID 37371868, 2023). "Inflammatory cytokines (interferons, TNF-α, IL-6, and IL-17) and inflammatory cells modulate the gene expression that regulates survival, proliferation, self-renewal, metastasis, and cancer stemness." (PMID 36979874, 2023). "In the anti-inflammatory assays, both PTS and PTSO were able to reduce the levels of three pro-inflammatory cytokines usually involved in the development of cancer: IL-8, IL-6, and IL-17." (PMID 36986093, 2023). "Taken together, these findings conclude that Fc-VFD inhibits the angiogenesis of endothelial cells by the inhibition of VEGF-A and IL-6 expression both from cancer and endothelial cells in the TME." (PMID 35895109, 2023). "Accordingly, PDGFB expression in cancer cells was significantly upregulated by IL6 and TGFB1 in vitro." (PMID 37658364, 2023). "In terms of biochemical mechanisms, NF-κB activation by the engagement of TLRs plays a pivotal role in cancer proliferation, survival, angiogenesis, and progression through the up-regulation of IL-6, Bcl-xL, Bcl-2, Bcl-xs, XIAP, and VEGF genes." (PMID 37287005, 2023). "Anti-IL-6 antibody (Siltuximab) is proven to have an anti-cancer effect and decreases not only CCL-2, but also VEGF and CXCL-12 expression." (PMID 36260158, 2023). "The application of IL-6 blockers as anti-cancer agents has been investigated in many cancer types, but the only currently approved monoclonal antibodies (mAbs) in the United States are tocilizumab (anti-IL-6Rα) and siltuximab (anti-IL-6)." (PMID 37047012, 2023). "The increase in IL-6 and CRP is typical for inflammaging, and both proteins are also elevated in cancer and their levels are associated with tumor progression and prognosis." (PMID 37895144, 2023). "IL-6 restrained effector differentiation of CD8+ T cells (also known as cytotoxic T lymphocytes, or CTLs), and high plasma IL-6 correlated with reduced effector gene expression in CTLs from cancer patients." (PMID 36599350, 2023). "In cancer, IL-6 can act in both autocrine and paracrine manners to direct the expression of downstream target molecules associated with cancer cell survival, proliferation, metastasis, and drug resistance." (PMID 37385076, 2023). "In return, the overexpression of Notch1/2 suppresses the expression of TLR4-induced proinflammatory cytokines, TNF-α, and IL-6 and favor cancer-promoting anti-inflammatory cytokine IL-10." (PMID 36765706, 2023). "In triple negative breast cancer cells with CIN, the depletion of cGAS–STING resulted in a reduction in IL-6 production and impaired cancer cell survival." (PMID 37534795, 2023). "In another study, treating cancer cells with platinum-based chemotherapy increased their secretion of IL-6 and prostaglandin E2 (PGE2) through an NF-κB mediated pathway." (PMID 37545408, 2023). "Secondly, in the present study, we focused on IL-6 as it is a key inflammatory cytokine involved in different types of cancer." (PMID 36990991, 2023). "The IL-6-driven acute phase response protein CRP (C-reactive protein) was similarly associated with plasma IL-6 and poor OS in all three cancer types." (PMID 36599350, 2023). "Increased levels of IL6 activity were observed in chronic inflammatory conditions and play a key role in growth and development in many cancers." (PMID 37370765, 2023). "According to the available data, this surge in the IL-6 concentration creates favourable conditions for cancer progression." (PMID 38201617, 2023). "IL-6 is produced by various cell types, including immune cells, stromal cells, and cancer cells themselves." (PMID 37892997, 2023).
cancer (continued). "HCC cells with higher migratory and invasive abilities secrete miR-1247-3p-rich exosomes that activate cancer-associated fibroblasts (CAFs) to enhance HCC metastasis, invasion, and EMT via IL-6 and IL-8." (PMID 37904170, 2023). "Many pro-inflammatory cytokines increase the concentration of TNFα and IL-6, which are the key cytokines in cancer progression." (PMID 36981858, 2023). "On the other hand, when incubating cancer cells with IL-6, IL-6 antibodies, and M1 macrophages, anti-IL-6 antibodies partially inhibit the effect that macrophages have on the cancer cells." (PMID 37958980, 2023). "The IL-6/STAT3 signaling pathway upregulates factors involved in cancer cell proliferation (MYC, cyclin D1), angiogenesis (VEGFA, PDGF), and apoptosis (Bcl-XL)." (PMID 36720310, 2023). "While myCAFs were mainly involved in extracellular matrix remodeling, iCAFs produced pro-inflammatory cytokines, including IL-6, an important player in cancer progression and wound healing." (PMID 37707642, 2023). "In CHX207 mice, deletion of IL‐6 exclusively in cancer cells was sufficient to prevent CAC even though host cells such as immune cells, myocytes, and adipocytes also produce high levels of IL‐6 in response to cancer." (PMID 36351437, 2023). "The relationship between blood IL-6 levels and survival has been reported in various cancers, but few studies have examined this relationship histologically." (PMID 36764954, 2023). "These cells secrete LIF and IL6, which are required to sustain cancer cell line growth and survival." (PMID 36602390, 2023). "The results were also supported by previous study, in which IL‐6 expression level in cancer patients was considered as a predictor of poor prognosis." (PMID 36419386, 2023). "Meanwhile, IL-17 mediates cancer promotion through induction of IL-6, and accordingly, an activation of IL-8 and both IL-6 and IL-8 were found to be decreased in their expression as a response to 13.4 mM of melatonin treatment." (PMID 36651944, 2023). "Deletion of IL‐6 from cancer cells also reduced Il‐6 mRNA expression in m.qu., iWAT, and gWAT of CHXIL6KO mice and resulted in a drastic reduction of plasma IL‐6 concentrations (−94%) as well as p‐STAT3 (Tyr705) levels in iWAT (−60%) and m.qu." (PMID 36351437, 2023). "Clinically, IL-1β, IL-18, IL-6, and MIC-1/GDF-15 levels are associated with the risk of carcinoma and the prognosis of established cancer." (PMID 37715239, 2023). "Increased production of pro-inflammatory cytokines such as IL-1β, IL-6, TNF-α and MCP-1 has also been linked to various types of cancer." (PMID 37173732, 2023). "Significantly higher IL-6 among depressed cancer patients compared to healthy subjects, and higher levels of inflammatory markers were associated with fatigue and sleep disturbance." (PMID 36717689, 2023). "Metastatic cancer cells can secrete many osteolytic factors, such as PTHrP, IL-6, TNF, etc., which stimulate OC proliferation and differentiation and produce osteolytic effects." (PMID 37746292, 2023). "There was a significantly higher production of IL-6 by fibroblasts compared to cancer cells in the corresponding groups." (PMID 38258051, 2023). "For example, IL-6, IL-1β, and TNF-α were increased at cancer early stage and associated with disease severity." (PMID 36899319, 2023). "Several reports showed that IL-6 and p-STAT3 levels were associated with poor clinical prognosis in several kinds of cancer." (PMID 36635302, 2023). "Many studies reported that IL-6 is an essential component for performing many functions such as the proliferation, metastasis, and hormonal regulation functions of cancer cells." (PMID 36903346, 2023). "Cancer cells can be characterized by overexpression of certain cytokines groups, e.g., IL-6 or IL-11." (PMID 38258051, 2023).
cancer (continued). "Immunohistochemical scores for IL‐6 were significantly increased in cisplatin‐treated animals (P = 0.032 vs. the cancer‐positive group) and decreased in mice treated with the combination therapy (P = 0.029 cisplatin vs. cisplatin plus DMAPT)." (PMID 37533407, 2023). "IL-6 is an SASP factor that causes EMT-like gene expression and drug resistance in surrounding cells, leading to cancer progression." (PMID 38003589, 2023). "IL‐6 acts directly on cancer cells to potentiate cancer progression, metastasis, angiogenesis, stemness, and chemoresistance." (PMID 37696858, 2023). "Another study on the paracrine effects of tumor-derived factors revealed that SPARC overexpression in cancer cells decreased macrophage and mesothelial production of IL-6, MMPs, urokinase plasminogen activator, prostaglandin E2, and 8-isoprostanes." (PMID 37545408, 2023). "Extracellular vesicles (EV) derived from cancer cells contained IL-6, which was sufficient to induce HSL phosphorylation and delipidation in adipocytes." (PMID 36672449, 2023). "It has been demonstrated that FTY720 blocks the SPHK1/S1P/S1PR1 axis, leading to the blockade of the NF-kB/IL-6/STAT3 amplification loop and colitis-associated cancer." (PMID 36714534, 2023). "Treatment of patients with cancer with immunecheckpoint inhibitors can stimulate the production of IL-6." (PMID 37720284, 2023). "IL-6 is a proinflammatory cytokine secreted by cancer cells that is involved in regulating the proliferation and differentiation of cancer cells." (PMID 36600313, 2023). "Because serum ferritin is an acute-phase protein in inflammatory and infectious processes and in cancer, the production of apoferritin is increased because of the stimulation of interleukins (ILs), such as IL-1 and IL-6." (PMID 37347744, 2023). "IL-6 secretion by fibroblasts seemed to be activated by the cancer cells under inflammatory and hypoxic conditions." (PMID 37947617, 2023). "Secreted inflammatory cytokines in cancer cells, including IL-22, IL-6, IL-8, IL-4, IL-1β, HGF, IGF-1, EGF, G-CSF, TNF-α, VEGF, and IL-11, can confer the promotion of chemo- and radioresistance." (PMID 38140352, 2023). "IL-6 was inhibited after curcumin treatment of cancer cells, and drug-resistant strains were resensitized to cisplatin." (PMID 36859398, 2023). "Inflammatory cytokines, such as IFN- γ, IL-1β, IL-2, IL-4, IL-6, IL-10, IL-12p70, and TNF-α, have been shown to be involved in the immune response associated with cancer progression." (PMID 37373987, 2023). "The JAK inhibitor tofacitinib eliminates Microsatellite instability (MSI) induced by IL-6 or neutrophils, potentially delaying or preventing the progression of cancer in cases of colitis." (PMID 38288125, 2023). "For example, higher levels of pro-inflammatory cytokines (e.g., IL-6, IL-8, TNFα) in peripheral blood before treatment were usually found to predict worse responses in various cancer types, including metastatic non-small-cell lung cancer and melanoma." (PMID 37887315, 2023). "LRP1B was revealed to suppress the activation of IL-6-JAK-STAT3 by several cancer-related previous studies." (PMID 38019868, 2023). "Addressing IL6 dysregulation is a well-established therapy in auto-immune disease, but little is known about its benefits for cancer patients." (PMID 37958474, 2023). "Cisplatin is known to aggravate cancer cachexia in a significant proportion of patients, a phenomenon thought to be partially mediated by IL‐6 and other pro‐inflammatory cytokines." (PMID 37533407, 2023). "The secretion of IL-6 by transformed M2 TAMs promotes cancer cells to express more YAP1, K-Ras, β-catenin, NF-κB, and mTOR and thus enhances the percentage of cancer stem-like cells." (PMID 37124519, 2023). "That indicated potential relationships between STAT and rejection of allograft, interferon response, inflammatory response and IL6-JAK-STAT3 signaling pathway in pan-cancer, which was consistent with relevant previous research." (PMID 36968603, 2023).
cancer (continued). "The findings revealed that CAFs play a significant role by secreting elevated levels of IL-6, promoting cancer growth and progression." (PMID 37892997, 2023). "Several reports highlight the role of IL-6 trans-signaling and activation of the STAT3 pathway in mediating an exaggerated activation of fibroblasts leading to their transformation into cancer-associated fibroblasts." (PMID 37049615, 2023). "Lunasin treatment of both cancer cell lines increased IL-6 gene and protein expression at 24 h and then decreased its protein production at 48 h while increasing COX-2 gene and PGE2 level at 24 h in MCF-7 cells but not in MDA-MB-231 cells." (PMID 36794014, 2023). "Lipolysis can be stimulated by molecules secreted by adipocytes under the influence of cancer cells, including interleukin-6, so we decided to examine the secretion pattern of molecules released by tested cells." (PMID 37481560, 2023). "Our observations have suggested that MDSC secreted IL-10/IL-6/IL-1β are the critical players modulating the drug resistance of cancer cells via STAT3/STAT1/NF-κB pathway." (PMID 38304256, 2023). "At the moment, lunasin first induced IL-6 production immediately to suppress cancer cell growth and subsequently decreased its secretion to maintain homeostasis, suggesting that lunasin regulated inflammation in this microenvironment." (PMID 36794014, 2023). "It has recently been demonstrated that IL-6 and IL-8 paracrine signaling in metastatic cancer cells increases motility in a cell density-dependent manner." (PMID 38187701, 2023). "So, the levels of IFN-β, C-X-C motif chemokine 10 (CXCL10), and IL-6 in cancer cells after various treatments and bone marrow-derived dendritic cells (BMDCs) incubated with pretreated cancer cells were measured." (PMID 37221157, 2023). "The PANoptosis score was positively correlated with many malignant pathways in pan-cancer, especially IL6-JAK-STAT3 signaling, interferon-gamma response, inflammatory response, IL2-STAT5 signaling, and TNF-a signaling via NF-kB signaling." (PMID 36890219, 2023). "It is becoming increasingly clear that CIN and DNA damage can trigger IL-6/STAT3 signaling in various cancer types, including breast cancer and ovarian cancer." (PMID 37561163, 2023). "There was a decrease in the number of Treg/CD4(+) and Treg/CD3(+) along with an increase in the cytotoxicity of the CIK cells against HCC in vitro, suggesting the potential use of IL-6 in improving cancer immunotherapy." (PMID 37892997, 2023). "Briefly, the M1 phenotype is responsible for anti-cancer effects through the production of pro-inflammatory cytokines such as tumour necrosis factor α (TNFα) and interleukin (IL-6)." (PMID 37894480, 2023). "IL-6 is generally an inflammation biomarker; however, elevated serous IL-6 is also observed in cancers." (PMID 36832045, 2023). "This TLR pathway can be targeted by drugs, such as IRAK-1 kinase and NF-kB1 inhibitors or IL-6 blocking antibodies, to reduce cancer progression." (PMID 36772305, 2023). "In the case of PCa bone metastasis, OBs recruit cancer cells to the bone surface by expressing various cytokines such as interleukin-6 (IL-6), transforming growth factor beta (TGF-β), insulin-like growth factors (IGFs) and Wnts." (PMID 36759880, 2023). "Interleukin (IL)-6 is higher in cancers with a highly invasive ability, and is closely related to the metastasis of cancers." (PMID 37501379, 2023).